LPL (lipoprotein lipase)
Diseases named in the same sentence as LPL in open-access papers (continued):
Sharing a sentence is not in itself a finding about the gene and the disease.
hypertriglyceridemia (continued). "LPL gene variants constitute the majority of genetic etiologic factors reported for neonatal cases with severe hypertriglyceridemia; however, many other genes are also involved with this phenotype." (PMID 33879184, 2021). "In the present study, a novel c.483delA (p.A162Pfs*10) frameshift mutation was found in LPL gene exon 4 of the infant with severe hypertriglyceridemia." (PMID 34485189, 2021). "Genetic studies have uncovered more than 100 LPL variants, the majority of which are loss-of-function variants in patients with hypertriglyceridemia." (PMID 34336854, 2021). "Lipoprotein lipase (LPL), a key enzyme that produces free fatty acids (FFAs), is involved in TG degradation and its loss of function causes severe hypertriglyceridemia." (PMID 34293055, 2021). "Through the rapid screening of all reported cases of neonatal hypertriglyceridemia with identified genetic etiology published in PubMed over the last 10 years (2011–2020), LPL gene variants were responsible for 73% of cases (45/62)." (PMID 33879184, 2021). "ApoC-II is necessary for LPL activation, acting as a cofactor, and severe hypertriglyceridemia has been reported in cases of apoC-II deficiency." (PMID 34895245, 2021). "Consistent with this hypothetical model, mice with collagen XVIII-deficiency (Col18–/–) have moderate hypertriglyceridemia and reduced plasma levels of LPL." (PMID 34336854, 2021). "Though LPL mutation in patients with hypertriglyceridemia has been reported, a combination of an LPL gene frameshift mutation with compound heterozygous mutations of the SLC37A4 gene is rare." (PMID 34485189, 2021). "Under normal circumstances, triglycerides are hydrolyzed by lipoprotein lipase while insufficiency of insulin causes hypertriglyceridemia and hypercholesterolemia." (PMID 33752586, 2021). "LPL deficiency is a rare disorder caused by a loss of function of the LPL gene, and patients with LPL deficiency usually have marked hypertriglyceridemia." (PMID 34485189, 2021). "LPL deficiency has been reported to contribute to hypertriglyceridemia in previous studies, and the rat model induced by P407 showed decreased LPL expression and activity and increased plasma TG levels." (PMID 34036306, 2021). "A set of 53 single nucleotide polymorphisms (SNPs) previously associated with triglycerides levels, as well as 37 rare variants within the five main genes associated with hypertriglyceridemia (i.e. LPL, APOC2, APOA5, LMF1 and GPIHBP1) were analyzed." (PMID 33588820, 2021). "Several genetic variants associated with hypertriglyceridemia are located in the interface between the N- and C-terminal domains of LPL (e.g., p.Ser259Arg, p.Gly409Arg, p.Glu410Val)." (PMID 34336854, 2021). "One such protein is the lipase maturation factor (LMF1), which is essential for LPL processing since loss-of-function variants in LMF1 cause hypertriglyceridemia due to inefficient LPL secretion." (PMID 34356847, 2021). "It has been observed in prior studies that mutations in the lipoprotein lipase (LPL) gene predispose to hypertriglyceridemia, conferring increased risk of CVD." (PMID 33505729, 2021). "A partial or complete LPL deficiency results in an inability to hydrolyze TGs in chylomicrons and very-LDLs, causing mild to severe hypertriglyceridemia." (PMID 34036306, 2021). "It was demonstrated that homozygous missense mutations (L252V) were found in the LPL gene of a newborn with hypertriglyceridemia in China." (PMID 34485189, 2021). "The LPL pathogenic variant in the proband is reported for the first time in homozygosity associated with neonatal severe hypertriglyceridemia." (PMID 33879184, 2021). "Our findings identified a novel LPL gene frameshift mutation combined with SLC37A4 gene compound heterozygous mutations in a GSD Ib infant with severe hypertriglyceridemia." (PMID 34485189, 2021).
hypertriglyceridemia (continued). "In conclusion, we found a novel frameshift mutation in the LPL gene that led to severe hypertriglyceridemia in a Chinese infant with GSD Ib, who was successfully treated with MCT milk." (PMID 34485189, 2021). "In this article, we reported a Chinese infant with GSD Ib who presented with severe hypertriglyceridemia with a novel frameshift mutation found in her LPL gene." (PMID 34485189, 2021). "Lipoprotein lipase (LPL) deficiency is a monogenic lipid metabolism disorder biochemically characterized by hypertriglyceridemia (HTG) inherited in an autosomal recessive manner." (PMID 34544385, 2021). "With this in mind, there is a great need to understand the underlining molecular mechanism(s) causing increased triglyceride levels in hypertriglyceridemia and atherosclerosis and map the complex regulation of LPL." (PMID 34356847, 2021). "The association of tissue hypertriglyceridaemia with cardiovascular disturbances observed in cadmium-exposed rats was associated with decreased LPL function, a key enzyme in TG hydrolysis." (PMID 34259114, 2021). "Here, we identified three mutations in LPL gene which causes severe hypertriglyceridaemia with acute pancreatitis in Chinese patients." (PMID 31901151, 2020). "Patients with genetic mutations of lipoprotein lipase (LPL) present severe hypertriglyceridaemia that evidenced the relevance of LPL." (PMID 32069954, 2020). "Variants on genes known to cause severe hypertriglyceridemia such as LPL, APOC2, GPIHBP1, APOA5, and LMF1 were first selected and interpreted." (PMID 32765589, 2020). "LPL deficiency leads to hypertriglyceridemia, whereas overexpression of LPL in a mice model resulted in insulin resistance and obesity." (PMID 32831121, 2020). "apoC-III is associated with hypertriglyceridemia via a number of pathways, including its action as an inhibitor of lipoprotein lipase (LPL) (the enzyme that metabolises TAGs from TRL to fatty acids and enables their clearance from the circulation)." (PMID 32494907, 2020). "Familial chylomicronemia syndrome (FCS) is a rare autosomal recessive disorder characterized by persistent extreme hypertriglyceridemia as a result of lipoprotein lipase deficiency." (PMID 32487261, 2020). "Hypertriglyceridaemia is a very rare disorder caused by the mutations of LPL gene, with an autosomal recessive mode of inheritance." (PMID 31901151, 2020). "Under diabetic condition, insulin resistance and/or deficiency inactivate lipoprotein lipase, which leads to a condition of a hyperglyceridemia." (PMID 31708869, 2019). "In homozygotes, the complete Angptl3 deficiency was associated with a highly reduced postprandial hypertriglyceridemia, probably due to an accelerated catabolism of intestinal derived TG-rich lipoproteins (chylomicrons) secondary to the increased LPL activity." (PMID 29752428, 2019). "In a recent study, the authors found a protective effect of lipoprotein lipase polymorphisms against hypertriglyceridemia in children under ARV therapy." (PMID 30941184, 2019). "Hypertriglyceridemia in CKD was associated with impaired triglyceride clearance caused by down-regulation of lipoprotein lipase and a very low-density lipoprotein receptor." (PMID 29472858, 2018). "Persons deficient in LPL enzyme levels are characterized by severe hypertriglyceridemia, while those with elevated LPL showed lower TG levels." (PMID 29632305, 2018). "In T2D insulin insufficiency or resistance leads to inactivation of lipoprotein lipase causes a condition of hypertriglyceridemia." (PMID 30545352, 2018). "Excessive circulating triglycerides due to reduction or loss of lipoprotein lipase activity contribute to hypertriglyceridemia and increased risk for pancreatitis." (PMID 29304082, 2018). "We conditionally knocked out lipoprotein lipase in differentiated striated muscle tissue lowering striated muscle lipoprotein lipase activity causing hypertriglyceridemia." (PMID 29304082, 2018).
hypertriglyceridemia (continued). "Previously generated mouse models for LPL deficiency are unable to mimic both the hypertriglyceridemia and decreased plasma LPL activity found in human patients." (PMID 29304082, 2018). "Deficiencies in LPL gene expression and/or function leads to variable hypertriglyceridemia in affected patients." (PMID 29304082, 2018). "Lipoprotein lipase (LPL) deficiency is an autosomal recessive genetic disorder characterized by extreme hypertriglyceridemia, with no cure presently available." (PMID 28969646, 2017). "Herein we have systematically characterized two novel loss-of-function mutations in LPL from a Chinese family in which afflicted members were manifested by severe hypertriglyceridemia and recurrent pancreatitis." (PMID 28548960, 2017). "In this study, we systematically characterized two novel loss-of-function mutations in LPL from a Chinese family in which afflicted members (except MC's daughter) were manifested by mild to severe hypertriglyceridemia and recurrent pancreatitis." (PMID 28548960, 2017). "Both mild-to-moderate and severe hypertriglyceridemia are primarily polygenic traits, with the exception of the small subgroup with monogenic chylomicronemia due to deficiency of lipoprotein lipase (LPL) and related factors." (PMID 28534127, 2017). "Familial chylomicronemia syndrome (FCS) with extreme hypertriglyceridemia is a disorder of lipoprotein metabolism due to loss-of-function mutations in the gene encoding LPL or ApoC-II." (PMID 26938273, 2016). "We identified previously known associations, such as variants in LPL associated with hyperglyceridemia indicating that our approach was robust." (PMID 27535653, 2016). "In this case, deficiency in LPL leads to severe hypertriglyceridemia, which can result in recurrent and potentially fatal pancreatitis." (PMID 27114411, 2016). "Severe hypertriglyceridemia usually occurs as a result of one or more genetic disorders, such as hyperlipoproteinemia or lipoprotein lipase (LPL) deficiency." (PMID 27444154, 2016). "Insulin deficiency depletes the activity level of lipoprotein lipase, thus leading to abnormal lipoprotein metabolism in diabetes and resulting in hypertriglyceridemia." (PMID 27037095, 2016). "We describe a novel mutation of the LPL gene causing severe hypertriglyceridemia and report the response to treatment." (PMID 26337181, 2015). "Decreased plasma activity of TG hydrolysis associated with adipose lipoprotein lipase (LPL) downregulation is responsible for the observed hypertriglyceridemia." (PMID 26268630, 2015). "Our patient is a compound heterozygote who has a novel p.Q240H mutation in exon 5 of the LPL gene causing severe hypertriglyceridemia." (PMID 26337181, 2015). "In contrast, APOC2 is a cofactor of LPL and its loss of function results in deficient LPL activity and consequent hypertriglyceridemia and chylomicronemia." (PMID 26044956, 2015). "The overexpression of human apo CIII in mice, rabbits and pigs has been shown to reduce lipoprotein lipase (LPL) activity and lead to hypertriglyceridemia, which is associated with atherosclerosis." (PMID 25836672, 2015). "Highlighted Article: Apoc2 loss-of-function zebrafish display severe hypertriglyceridemia, which is characteristic of human patients with defective lipoprotein lipase activity." (PMID 26044956, 2015). "One important clinical complication of hypertriglyceridemia in patients with LPL or APOC2 deficiency is recurrent pancreatitis, but the underlying mechanisms are poorly defined." (PMID 26044956, 2015). "Patients with APOC2 or LPL deficiency show severe hypertriglyceridemia and chylomicronemia, and often manifest eruptive xanthomas, lipemia retinalis and acute and recurrent pancreatitis, which can be lethal." (PMID 26044956, 2015). "Hypertriglyceridemia in LMF1-/- pups was due to combined lipase deficiency as demonstrated by dramatically reduced post-heparin LPL and HL activities." (PMID 25302068, 2014).
hypertriglyceridemia (continued). "Recent report showed that hypertriglyceridaemia induced by the loss of LpL was associated with reduced TG uptake into brown adipose tissue, but white adipose tissue fat accumulation was normal." (PMID 25148848, 2014). "Alterations or mutations in the lipoprotein lipase (LPL) gene contribute to severe hypertriglyceridemia (HTG)." (PMID 24646025, 2014). "It is well known that LPL is the rate-limiting enzyme for the hydrolysis of TG in core of TRLs and deficiency of this enzyme induces severe hypertriglyceridemia in humans and mice." (PMID 25148848, 2014). "Previous studies have demonstrated that the development of hypertriglyceridemia is closely associated with the downregulation of LPL activity." (PMID 23942585, 2014). "Among the 71 patients with history of major hypertriglyceridemia included, molecular assessment was available for 62 patients; all of which were examined for LPL gene mutations." (PMID 24788417, 2014). "Hypertriglyceridemia in end-stage renal disease is accompanied by impaired clearance of triglyceride-rich lipoproteins caused by dysregulation of lipoprotein lipase, hepatic lipase, or the very low-density lipoprotein receptor." (PMID 24367663, 2013). "In a study of Chinese population with type 2 diabetes and hypertriglyceridemia, 10 mutations were found in the LPL genes of diabetic patients." (PMID 24086538, 2013). "The four missense mutations, which occurred in the highly conservative amino acid sites in exons 3, 5, and 6, caused LPL dysfunction and hypertriglyceridemia." (PMID 24086538, 2013). "Genetic defects in LPL are responsible for the reduction in TG-rich lipoprotein clearance, and mutations in the LPL gene play important roles in the development of hypertriglyceridemia in the general population." (PMID 24086538, 2013). "Accordingly, mice deficient in lipoprotein lipase exhibited severe hypertriglyceridaemia and enhanced susceptibility to acute pancreatitis." (PMID 23028532, 2012). "Severe hypertriglyceridemia (HTG) has been linked to defects in LPL, APOC2, APOA5, LMF1 and GBIHBP1 genes." (PMID 23151256, 2012). "The depressed activity of insulin-mediated lipoprotein lipase (LPL) made the clearance rate of lipoprotein descend, which is the main cause of hypertriglyceridemia in T2DM disease." (PMID 21716678, 2012). "Total LPL deficiency in humans (type I hyperlipoproteinemia) is associated with severe hypertriglyceridemia and hypo-alpha-cholesterolemia." (PMID 21980507, 2011). "The simulation results are therefore consistent with hypertriglyceridemia resulting from LPL mutations, as previously demonstrated with the mouse knockout model." (PMID 20959003, 2010). "For example, just five of 123 patients with severe hypertriglyceridaemia (triglycerides>22.58 mmol/L) were deficient in LPL." (PMID 19534808, 2009). "Hypertriglyceridemia is characterized by elevated levels of plasma triglycerides caused, among others, by deficiencies of the lipoprotein lipase (LPL), the key enzyme in the catabolism of triglyceride-rich lipoproteins by removing (hydrolyzing) triglycerides." (PMID 18497853, 2008). "Naturally occurring LPL gene mutations have also been reported in the human population that lead to severe hypertriglyceridemia." (PMID 17971230, 2007). "Two major questions arose during the treatment aimed at lowering the severe hypertriglyceridemia in this pregnant LPL-deficient patient." (PMID 15610556, 2004). "This LPL-deficient subject developed severe hypertriglyceridemia in early pregnancy, with eruptive xanthomas and pancreatitis." (PMID 15610556, 2004). "The management of severe hypertriglyceridemia in a pregnant patient with LPL deficiency is directed toward preventing pancreatitis in the mother and delivery of a healthy infant." (PMID 15610556, 2004).
hypertriglyceridemia (continued). "Hypertriglyceridemia, hypovitaminosis, and cancer all contribute to a deficiency in LPL activity." (PMID 39940314, 2025). "Movement of lipoprotein lipase (LPL) from myocytes or adipocytes to the capillary lumen is essential for intravascular lipolysis and plasma triglyceride homeostasis—low LPL activity in the capillary lumen causes hypertriglyceridemia." (PMID 39814316, 2025). "There is some controversy whether heterozygosity for LPL loss-of-function variants is sufficient to cause moderate-to-severe hypertriglyceridemia." (PMID 40004987, 2025). "Previous data have shown that a decrease in LPL activity is the main cause of hypertriglyceridemia." (PMID 40284815, 2025). "Reduced LPL activity contributes to hypertriglyceridemia, a major cardiovascular risk factor." (PMID 41332650, 2025). "Notably, IL-1β has been implicated in inducing hypertriglyceridemia by inhibiting the activity of lipoprotein lipase (LPL) and suppressing lipogenesis." (PMID 40433411, 2025). "Not long ago, ApoC3 polymorphisms were associated with the lean male population’s susceptibility to NAFLD and insulin resistance leading to a rise in ApoC3 plasma levels by approximately 30% and postprandial hypertriglyceridemia caused by ApoC3’s altering effect on lipoprotein lipase activity." (PMID 38921259, 2024). "LPL deficiency triggers severe hypertriglyceridemia, whereas its overexpression may lead to insulin resistance and obesity." (PMID 38256272, 2024). "Patients with CREBH deficiency exhibit hypertriglyceridemia as a result of reduced LPL activity." (PMID 38521668, 2024). "LPL deficiency in the heart results in hypertriglyceridemia and cardiac dysfunction." (PMID 38973609, 2024). "Also, LPL deficiency in zebrafish causes severe hypertriglyceridemia, with plasma TG levels over 2,000 mg/dL." (PMID 39435661, 2024). "Heparin releases stored LPL from endothelial cells that may result in a transient increase in LPL activity but eventually depletes vascular endothelium from LPL and, thereby, causes rebound hypertriglyceridaemia." (PMID 37233662, 2023). "Our results showed a high frequency of H+H+ LPL-Hind III polymorphism in those with hypertriglyceridemia, which may be a hereditary indicator of vulnerability to this condition in the Kurdish population." (PMID 37954769, 2023). "Our results indicated that genotypes characterized by the H+H+ LPL-Hind III polymorphism may be hereditary indicators of vulnerability to hypertriglyceridemia in the Kurdish population." (PMID 37954769, 2023). "Some GSD1a patients may also present with hypertriglyceridemia, which can obviously mimic LPL deficiency." (PMID 37630727, 2023). "Inhibition of LPL predisposes to hypertriglyceridemia because of increased chylomicron remnants." (PMID 37304843, 2023). "In those with severe hypertriglyceridemia, the most frequent alleles were H+H+ LPL-Hind lll polymorphism (42, 65.6%) followed by A1A1 APO Cll-Ava ll polymorphism (30, 46.9%), whereas these frequencies were 16 (44.4%) and 6 (16.7%) in those with normotriglyceridemia, respectively." (PMID 37954769, 2023). "Under normal settings, insulin triggers the lipoprotein lipase enzyme that separates triglycerides; however, in diabetes, lipoprotein lipase is not stimulated because of insulin inadequacy, hence producing hypertriglyceridemia which is a leading cause of cardiac disorders." (PMID 37110767, 2023). "A complete loss of LPL causes fasting hyperchylomicronemia with severe hypertriglyceridemia." (PMID 38303975, 2023). "The H+H+ LPL-Hind lll polymorphism was the most frequent allele pair in patients with severe hypertriglyceridemia, as compared to those with normotriglyceridemia, indicating its role as a genetic indicator of vulnerability to severe hypertriglyceridemia in the Kurdish population." (PMID 37954769, 2023).